FGFR3 (fibroblast growth factor receptor 3)
Diseases named in the same sentence as FGFR3 in open-access papers (continued):
Sharing a sentence is not in itself a finding about the gene and the disease.
cholangiocarcinoma (35 papers, 2016 to 2025). A carcinoma that arises from the intrahepatic biliary tree (intrahepatic cholangiocarcinoma) or from the junction, or adjacent to the junction, of the right and left hepatic ducts (hilar cholangiocarcinoma). "For example, erdafitinib is approved for treating locally advanced or metastatic urothelial cancer patients with FGFR2/FGFR3 mutations, and pemigatinib is approved for treating cholangiocarcinoma with FGFR2 fusion/rearrangement." (PMID 39583123, 2024). "It has become clear that abrogating aberrant FGFR signalling in urothelial cancer (driven by FGFR3 mutations) and cholangiocarcinoma (driven by FGFR2 fusions) has led to improved clinical outcomes in these molecularly defined patient populations." (PMID 33268819, 2021). "Based on clinical experience in adult cancers, it has become clear that aberrant FGFR-mediated signaling is predictive of response to FGFR inhibitors in urothelial cancer (mainly driven by FGFR3 mutations) and cholangiocarcinoma (mainly driven by FGFR2 fusions)." (PMID 40510032, 2025). "Of note, the characteristics of the FGFR3 kinase domain at resistance are distinctly different from what has been observed in FGFR2-driven cholangiocarcinoma." (PMID 37377403, 2023). "Currently, erdafitinib and pemigatinib are approved for use in the United States for metastatic urothelial carcinoma with FGFR2 or FGFR3 aberrations and for cholangiocarcinoma with an FGFR2 rearrangement, respectively." (PMID 34247193, 2021). "Unlike urothelial cancer, which has a high rate of FGFR3 mutations, cholangiocarcinoma harbours an increased frequency of fusions or rearrangements that favour FGFR2 and a diverse group of partner genes." (PMID 33268819, 2021). "Thus far, erdafitinib and pemigatinib are the first FDA-approved FGFR selective inhibitors for treating urothelial cancer with FGFR2 or FGFR3 alterations, and cholangiocarcinoma with FGFR2 fusions and rearrangements, respectively." (PMID 33898310, 2021). "Notably, several next-generation FGFR inhibitors have shown preclinical activity and preliminary clinical activity in patients with cholangiocarcinoma harboring FGFR2 kinase domain mutations and urothelial cancer harboring FGFR3 kinase domain mutations following previous FGFR inhibitor treatment." (PMID 38710951, 2024). "Pemigatinib and futibatinib are approved for advanced cholangiocarcinoma with FGFR2 fusions, while erdafitinib is approved for metastatic urothelial carcinoma with FGFR2 or FGFR3 alterations." (PMID 41373672, 2025). "For instance, pemigatinib has received approval for the management of advanced cholangiocarcinoma because of its potent activity as a selective oral small-molecule inhibitor of FGFR1, FGFR2, and FGFR3." (PMID 40898491, 2025). "Pemigatinib, a kinase inhibitor used to treat locally advanced or metastatic, unresectable cholangiocarcinoma in adults by inhibiting FGFR1, FGFR2, and FGFR3, has been approved by the FDA." (PMID 38845691, 2024). "Several FGFR inhibitors demonstrated activity in cholangiocarcinoma and urothelial cancer harboring FGFR2 and FGFR3 alterations." (PMID 37681152, 2023). "Of note, EGFR bypass activation has been reported as an early event in the setting of FGFR inhibition in FGFR3-altered urothelial cancer and in FGFR2-driven cholangiocarcinoma, suggesting the potential of EGFR targeting in progressive FGFR-driven diseases." (PMID 37377403, 2023). "Pemigatinib, a small molecule inhibitor of FGFR1–3, has been approved in the US for treatment of unresectable cholangiocarcinoma with FGFR2 alterations, while erdafitinib, pan-FGFR inhibitor, is indicated for metastatic urothelial carcinoma with FGFR2 and FGFR3 alterations." (PMID 40393028, 2025).
cholangiocarcinoma (continued). "While rare in most cancers, these fusions indicate poor prognosis and are candidates for FDA-approved FGFR-targeted therapies, including infigratinib, pemigratinib and futibatinib for cholangiocarcinoma with FGFR2 fusions and erdaftinib for urothelial cancers with FGFR3 fusions." (PMID 40711866, 2025). "The promising results of pemigatinib and infigratinib in advanced unresectable cholangiocarcinoma harboring FGFR2 fusions or rearrangement, and erdafitinib in metastatic urothelial carcinoma with FGFR2 and FGFR3 genetic aberrations, lead to their accelerated approval by the United States (USA) FDA." (PMID 34199304, 2021). "In addition to patients with cholangiocarcinoma, we saw polyclonal acquired resistance in patients with FGFR2-altered gastroesophageal/gastroesophageal junction cancer and cancer of unknown primary origin, FGFR3-altered non-small cell lung cancer and FGFR1-altered pancreatic cancer." (PMID 38710951, 2024).
dwarfism (35 papers, 2003 to 2025). "When the ACH-associated mutations were inserted into mouse models, the FGFR3-altered mice exhibited a dwarfism characterized by short limbs, a small rib cage, craniofacial abnormalities, and a reduced foramen magnum." (PMID 40178985, 2025). "Among these, a homozygous FGFR3 variant (G380R) in case 3084 was inherited from the parents of the proband affected by dwarfism, which is a rare finding." (PMID 37880672, 2023). "FGFR3 regulates a wide range of physiological processes and its aberrant signaling has been linked to dwarfism, overgrowth, and several types of malignancies." (PMID 37345656, 2023). "Further pedigree analysis revealed that the homozygous FGFR3 variant (c.1138G > A, p.G380R) was inherited from the proband’s parents affected by dwarfism." (PMID 37880672, 2023). "Conversely, mice expressing a Fgfr3-activating mutation develop dwarfism and have reduced linear growth and impaired endochondral ossification, with reduced chondrocyte proliferation and reduced hypertrophic differentiation." (PMID 33986191, 2021). "FGFR3 gain-of-function mutations are also associated with mild dwarfism (hypochondroplasia) and severe dwarfism (thanatophoric dysplasia I and II)." (PMID 33737326, 2021). "Hepatic Fgfr3 is also repressed in mouse models of genomic instability, which exhibit dwarfism and GH-IGF1-signaling deficiency, thus paralleling our findings in Ames dwarf mice." (PMID 30462643, 2018). "FGFR germline mutations (activating) can cause skeletal disorders, primarily dwarfism (generally mutations in FGFR3) and craniofacial malformation syndromes (usually mutations in FGFR1 and FGFR2)." (PMID 26224133, 2015). "Since the discovery of the Gly380Arg mutation as the genetic cause for human dwarfism, research in the field has focused on the effect of this mutation on FGFR3 signaling." (PMID 23056398, 2012). "Here we seek insight into how different FGFR3 mutations cause the same dwarfism phenotype, and we thus compare the phosphorylation of two mutants linked to the same phenotype, ACH." (PMID 22529939, 2012). "FGFR germline mutations (activating) can cause skeletal disorders, primarily dwarfism (generally mutations in FGFR3), and craniofacial malformation syndromes (usually mutations in FGFR1 and FGFR2); intriguingly, some of these activating FGFR mutations are also seen in human cancers." (PMID 26224133, 2015). "In addition to differential skeletal size observed in sheep carrying mutations in FGFR3, greater than 95% of human dwarfism achondrodysplasia cases are caused by a gain-of-function mutation in FGFR3." (PMID 18940000, 2008). "Infigratinib, a pan-FGFR1/2/3 inhibitor, showed proof-of-concept activity in an FGFR3-driven murine model of dwarfism and subsequently entered clinical trials in children with ACH." (PMID 40178985, 2025). "Here, to define relevant genes controlling ciliogenesis in FGFR3-related dwarfism, we performed a comparative, longitudinal, transcriptomic analysis of RNA isolated from cartilage growth plates of Fgfr3Y367C/+ mice versus controls." (PMID 35078974, 2022). "The dwarfism phenotypes in ACH patients and mouse models, as well as the skeletal overgrowth with tall stature in CATSHL syndrome patients and Fgfr3 deficient mice strongly demonstrate that FGFR3 is a negative regulator of development of endochondral bone 4,8." (PMID 32641982, 2020). "Elevated FGF signaling in the growth plate is the pathological mechanism leading to another form of dwarfism (i.e., achondroplasia) and a soluble form of FGFR3 (sFGFR3) was recently evaluated in a clinical trial for treating this dwarfism." (PMID 33050204, 2020). "Both activating mutations in fibroblast growth factor receptor 3 (FGFR3) and inactivating mutations of guanylyl cyclase B (GC-B), also called NPRB or NPR2, cause human dwarfism." (PMID 29035170, 2017). "Similarities between human and canine phenotypes suggest a potential role for FGFR3 in different dog breeds displaying dwarfism." (PMID 18940000, 2008).
dwarfism (continued). "Studies based on transgenic mice models showed that mutant FGFR3 leads to dwarfism and infertility." (PMID 40282353, 2025). "Down-regulation of Fgfr3 could thus be a candidate mechanism for exploring the signaling effects of both dwarfism and DR." (PMID 30462643, 2018). "The highly prevalent point mutation in the FGFR3 gene might be genetically engineered so that we can treat ACH, a common form of dwarfism." (PMID 30381765, 2018). "Since all mutations in FGFR3 causing dwarfism are activating mutations, it is not likely that sequencing the coding region will miss a pathogenic mutation." (PMID 25614871, 2014). "The phenotype observed in dwarfism suggests that the dysregulation of FGFR3 could impair cell growth and differentiation, knockout mouse studies confirming an inhibitory role for FGFR3 in bone growth." (PMID 14520460, 2003). "In addition, the FGFR3 G380R variant was found in the father with dwarfism, but not in the fetus with skeletal dysplasia, indicating the added value of trio WES." (PMID 37880672, 2023). "We find that this mutation does not increase FGFR3 phosphorylation and decreases FGFR3 cross-linking propensity, a finding which raises questions whether this mutation is indeed a genetic cause for human dwarfism." (PMID 22529939, 2012).
craniosynostosis (33 papers, 2006 to 2024). Craniosynostosis is defined as the premature fusion of one or more cranial sutures leading to secondary distortion of skull shape resulting in skull deformities with a variable presentation. "Muenke syndrome in humans, characterized by craniosynostosis with uni- or bicoronal synostosis, comes from an FGFR3 Pro250Arg mutation resulting in the increased binding affinity of FGFR3 to its ligand, such as FGF9, by the substitution of a bulkier residue." (PMID 37325554, 2023). "Craniosynostosis syndromes are frequently associated with mutations in fibroblast growth factor receptors (FGFR2 or FGFR3) which play an important role in bone growth, particularly during embryonic development and are complexed with ECM components." (PMID 33974636, 2021). "A similar phenotype is seen in the mouse model of Muenke syndrome – a form of craniosynostosis caused by FGFR3 overactivation." (PMID 33737326, 2021). "This is clearly shown by the variants of NSD1 in cases 1 and 2, who were later assigned as affected by Sotos syndrome, and the variants identified in ERF, FGFR1, and FGFR3, all genes associated with craniosynostosis and, rather frequently, Chiari malformation." (PMID 33337535, 2021). "Muenke syndrome, the most common form of craniosynostosis, is also due to a single FGFR3 gain-of-function mutation." (PMID 33737326, 2021). "In conclusion, the authors mention that all patients with coronal craniosynostosis should be tested for the pathogenic variant p.Pro250Arg in the FGFR3 gene, to confirm the diagnosis of MS." (PMID 32510873, 2020). "It was found that the mutations in FGF receptors FGFR1, FGFR2, and FGFR3 in humans are associated with craniosynostosis, a characteristic phenotype of the Saethre-Chotzen Syndrome caused by dominant loss-of-function TWIST1 mutations." (PMID 24971743, 2014). "The identification of the P250R mutation in FGFR3 occurring in 20 unrelated families served as the definition of this craniosynostosis syndrome." (PMID 20108486, 2009). "Our main objective was to determine whether Twist1, FGFR1, FGFR2, or FGFR3 were the sites of causative mutation within our rabbit model of craniosynostosis." (PMID 23738319, 2013). "Interestingly, mutations in the same FGFR (either FGFR1, FGFR2 or FGFR3) can result in different craniosynostosis syndromes, thus implicating a common pathologic mechanism with FGFR gain of function in Pfeiffer, Apert, Muenke, and Beare-Stevenson syndromes." (PMID 16740155, 2006). "Genes most commonly mutated in familial craniosynostosis include, besides FGFR2 and FGFR3, the twist family bHLH transcription factor 1 (TWIST1) and ephrin-B1 (EFNB1)." (PMID 37441579, 2023). "In humans, FGFR mutations have been associated with craniosynostosis in patients with Apert and Crouzon syndromes (FGFR2 gain-of-function mutation) and Muenke syndrome (FGFR3 gain-of-function mutation)." (PMID 37325554, 2023). "At one or both ages, this population expresses the craniosynostosis-related genes Alpl, Fgfr2, and Fgfr3 as marker genes." (PMID 34880220, 2021). "In this study, we describe the main clinical characteristics of 36 patients with craniosynostosis, as well as some of the pathogenic variants of FGFR1, FGFR2, FGFR3, and TWIST1 genes." (PMID 32510873, 2020). "The presence of craniosynostosis had already been investigated through the analysis of the FGFR3 and the FGFR2, the result was normal." (PMID 31578813, 2020). "The suggested genetic causes of craniosynostosis are pathogenic variants in FGFR1, FGFR2, FGFR3, and TWIST1 genes." (PMID 32510873, 2020). "In fact, the majority of mouse craniosynostosis models resulting from FGF signaling aberrations have been generated using activating mutations in FGF receptors, particularly Fgfr2 and Fgfr3." (PMID 29752281, 2018). "A genetic cause accounts for ∼25% of craniosynostosis cases, most frequently due to coding mutations in FGFR2, FGFR3, and TWIST1 (Wilkie, Johnson, & Wall, 2017)." (PMID 30040876, 2018).
craniosynostosis (continued). "The most commonly mutated genes in syndromic craniosynostosis include FGFR2, FGFR3, and FGFR1, comprising the FGFR family." (PMID 29093661, 2017). "A prescreen for mutations in the craniosynostosis genes FGFR1, FGFR2, FGFR3, and TWIST was performed and mutations identified in approximately 50% of cases (B. Wollnik, pers." (PMID 24498618, 2013). "The most common and well-characterized cases of craniosynostosis have been caused by mutation in the FGFR1 (fibroblast growth factor receptor 1), FGFR2, FGFR3, TWIST and MSX2 (muscle segment homebox 2) genes." (PMID 20108486, 2009). "Although FGFR3 gene variants are associated with Muenke and Crouzon syndromes manifested by craniosynostosis, this feature, surprisingly, was not exhibited in the FGFR3 A385E/+ mice model." (PMID 37441579, 2023). "Targeted PCR and Sanger sequencing of FGFR1, FGFR2, FGFR3, TWIST1, and TCF12 genes resulted in the highest diagnostic rate in our cohort of craniosynostosis patients strongly recommend analysing those genes first (isolated CS and syndromic CS without intellectual disability)." (PMID 35591945, 2022). "The clinical hypothesis of craniosynostosis remained convincing and thus, molecular investigation of the FGFR3 and TWIST1 genes and array-CGH analysis to search for microdeletions/duplications were performed, all with negative results." (PMID 35885943, 2022). "Thus, the goal of this study was to describe the major clinical features associated with craniosynostosis, as well as to identify the frequency of pathogenic variants in FGFR1, FGFR2, FGFR3, and TWIST1 in a sample of Mexican patients." (PMID 32510873, 2020). "The variant is very rare and falls in a transmembrane domain which is not involved in achondroplasia, craniosynostosis, or other skeletal FGFR3-associated dysplasia, although in some of these dysplasias Chiari malformations, of either type 1 or 2, are reported." (PMID 33337535, 2021). "However, FGFR3 has not been reported to be the genetic cause of heterotaxy to date and has rarely been shown to be related to cardiac abnormalities, except for one case of FGFR3-related craniosynostosis combined with a cleft mitral valve." (PMID 35518361, 2022). "Overall, craniosynostosis affected 2 out of 42 patients in our cohort (5%), who both underwent direct sequencing of FGFR2, FGFR3, FGFR1 and TWIST1, with normal results." (PMID 29093661, 2017). "Mutations in the genes encoding fibroblast growth factor receptors 1, 2 and 3 (FGFR-1, FGFR-2, FGFR-3), TWIST and MSX2 (muscle segment homebox 2) have been identified in certain syndromic craniosynostosis." (PMID 20108486, 2009). "DNA analysis for a specific craniosynostosis syndrome was performed, and no pathogenic variants were found in the FGFR1 (OMIM #136350), FGFR2 (OMIM #176943), FGFR3 (OMIM #134934), and TWIST (OMIM #601622) genes." (PMID 34733861, 2021). "To date, we have tested, by dideoxy‐sequencing of TCF12, 105 Dutch syndromic and nonsyndromic coronal craniosynostosis index patients with negative results for FGFR2, FGFR3, and TWIST1 testing." (PMID 27158814, 2016).